SOX4 (SRY-box transcription factor 4)
Diseases named in the same sentence as SOX4 in open-access papers (continued):
Sharing a sentence is not in itself a finding about the gene and the disease.
cancer (continued). "These included genes involved in cell death and survival processes (BCLAF1, CFLAR, CASP1, and XIAP), genes associated with proliferation-driving transcription or cancer (KLF4, LEF1, SOX4, ID3), and genes associated with inflammation (CD28, CCR7, CX3CR1 and IFNG)." (PMID 28407008, 2017). "Furthermore, co-knockdown with sh-Slug and sh-Sox4 synergistically rescued miR-204-supressing cancer stemness and EMT properties." (PMID 26933999, 2016). "SOX4 is over-expressed in several cancers and has prognostic significance." (PMID 26555193, 2015). "Recently, multiple studies have revealed aberrant expression of SOX4 in several human cancers." (PMID 26583330, 2015). "Several evidences have showed SOX4 expression may inhibit cell apoptosis, increase cell invasion and metastasis, and maintain cancer-initiating cells." (PMID 26578818, 2015). "SOX4 expression has also been reported to be highly expressed in various cancer tissues." (PMID 26555193, 2015). "Reportedly, SOX4 expression results in alterations of oncogenic phenotypes, including inhibition of apoptosis, cell-cycle progression and irradiation-induced apoptosis, and promotion of epithelial to mesenchymal transition in a variety of cancer cells." (PMID 26555193, 2015). "MCF 10C also expresses high levels of Nanog, and Sox4, which are markers of cancer stem cells." (PMID 24528676, 2014). "There were also gene sets related to cancer signaling pathways (MYC, STAT3, and CDH1) or genes moderately involved in cancer (IRF4, SOX4, and EZH2), as well as some associated with various aspects of cancer such as cell transformation, metastasis, and response to therapeutics." (PMID 25122487, 2014). "In addition, restoration of miR-129-2 by cell transfection also led to decreased SOX4 expression and reduced proliferation of cancer cells." (PMID 25344911, 2014). "SOX4 was previously shown to enhance beta-catenin/TCF activities in several cancer types." (PMID 25366337, 2014). "Future insight into the regulation of SOX4 and its downstream target genes in the context of cancer development and progression, could prove useful to design pharmacological compounds which modulate the activity of this important transcription factor." (PMID 23301048, 2013). "Furthermore, the well-known cancer-associated genetic factors MMP2 and SOX4 co-emerged in the identified interactions." (PMID 23782521, 2013). "The SOX4 gene encodes a 47 kDa protein of the SOX family, which may play roles in the development of cancer cells." (PMID 22510499, 2012). "The expression of SOX4 in human cancers varies according to cancer type." (PMID 23285187, 2012). "This novel interaction between SOX4 and plakoglobin may provide insights into the role of SOX4 in key pathways in cell proliferation, development, and cancer progression." (PMID 22098624, 2011). "Furthermore, in two independent cohorts of microsatellite-stable stage II cancers we found that high SOX4 transcript levels correlated with recurrence (HR 2.7; 95% CI, 1.2–6.0; P=0.01)." (PMID 19156145, 2009). "Indeed, the prognostic values of SOX4 have previously been reported in some malignant tumors." (PMID 37958409, 2023). "Moreover, various reports suggest that SOX4 can aid in predicting marker in some cancer types." (PMID 33995626, 2021). "However, despite the small number of cases, our results suggest that SOX4 immunohistochemical staining may provide a valuable tool in addressing the challenge of differential diagnosis for these cancers." (PMID 33923245, 2021). "Our bioinformatics study showed that HDAC1 may mediate the regulatory effect of SOX4 on several important signaling pathways associated with stem cell maintenance, including Wnt (module 4), PPAR, Notch and transcriptional misregulation in cancer." (PMID 33482915, 2021). "Multiple researches reported that SOX4 could be regulated by lots of miRNAs in human cancers." (PMID 34258391, 2021).
cancer (continued). "SOX4 is an important member of SOX family of transcription factors and participates in cancer development and progression by the transcriptional activation of downstream target genes in cancer-associated signaling pathways 54, such as PI3K pathway, Wnt pathway, and TGF-β pathway." (PMID 34234874, 2021). "The identification of this novel SOX4 controlled pathway underscores the validity of our approach and highlights the value of our dataset as a resource to uncover further novel functions for SOX4 in cancer and potentially to understand its role in developmental biology." (PMID 30507376, 2018). "Notably, overexpression of SOX4 is observed in a variety of human cancers." (PMID 25644061, 2015). "TGF-β was commonly expressed by multiple cell types, including cancer cells, stromal cells and BECs, and its expression was upregulated in metastatic LNs, potentially driving the expression of MGP, FN1, SOX4, PDPN, and HEY1 in LECs." (PMID 41249124, 2025). "TEAD inhibitor induces SOX4 expression via upregulation of VGLL3, promoting cancer cell survival and resistance to TEAD inhibitors via activating the PI3K/AKT signaling pathway." (PMID 38331879, 2024). "miR-320a directly targets SRY-Box Transcription Factor 4 (SOX4) and Forkhead Box M1 (FOXM1) and exerts a cancer-suppressive effect on CRC." (PMID 38315263, 2024). "Krüppel-like factor 4 (KLF4) is a common downregulated TF in cancer that would inhibit IFITM3 and SOX4 expression." (PMID 39228892, 2024). "The IPA summary of contralateral PTE+ cortical astrocytes shows predicted activation of serine peptidase inhibitor Kazal type 1 (SPINK1) general cancer pathway, as well as IL-15 production, KLF4, SOX4 and migration of phagocytes/myeloid cells." (PMID 38600221, 2024). "We first explored an established cancer stemness marker, CD24 and an EMT marker for SOX4 expression." (PMID 38203779, 2024). "ADSL silencing significantly upregulated the mRNA and protein expression levels of cancer stem cell–related transcription factors, namely, Oct-4, Nanog, KLF4, and SOX4, as indicated by qRT-PCR and Western blotting." (PMID 37976135, 2023). "Cancer stem cells harbor the properties of cancer cells and stem cells simultaneously, and several typical stemness factors have been proven to modulate CSC maintenance, including c-Myc, Sox2, and Sox4." (PMID 38933287, 2023). "Several studies have indicated that SOX4 also plays a critical role in EMT regulation, which can facilitate metastasis and chemoresistance in carcinomas." (PMID 36766786, 2023). "Within the cancer-enriched constituent enhancers of SE60, we found SOX4, ATF4, and YY1 as the top three predicted transcription factors." (PMID 35869079, 2022). "Cancer cells in the S components upregulated SOX4 and CEACAM5 and downregulated pro-inflammatory factors such as SCGB1A1 and SFTPC in comparison with cancer cells in the GG components." (PMID 35874770, 2022). "SOX family members, including SOX4, SOX9, and SOX15, are very often studied in relation to cancer and were observed to be related to the suppression of the Wnt/β-catenin pathway." (PMID 35328735, 2022). "The in-situ cancer-2 population shows a strong and specific expression of TMEM59 and SOX4, which both can promote apoptosis." (PMID 35835774, 2022). "We further reveal that TEAD inhibition or YAP/TAZ silencing leads to VGLL3-mediated transcriptional activation of SOX4/PI3K/AKT signaling axis, which contributes to cancer cell survival and confers therapeutic resistance to TEAD inhibitors." (PMID 36347861, 2022).
cancer (continued). "SOX4 (SRY-related HMG-box 4) is related to cell fate differentiation and determination in male testis fertility, as well as cancer development and progression." (PMID 36101460, 2022). "Expression and phylogenetic tree analyses of the SOX gene family revealed that the expression of three closely related SOX members, SOX4, SOX11, and SOX12, was increased in multiple cancers." (PMID 34442467, 2021). "The analysis of SOX4, SOX11, and SOX12 expression revealed that their expression was correlated with patient survival in several types of cancers." (PMID 34442467, 2021). "This work reveals a novel underlying mechanism, SOX4-HDAC1 axis, for stemness maintenance of human cancer and suggests that HDAC1 inhibition should be an effective precision therapeutic strategy for eradicating SOX4-drived human CSCs." (PMID 33482915, 2021). "In the present study, we revealed that phylogenetically close SOX members, SOX4, SOX11, and SOX12, have distinctively higher expression in various cancers, and analyzed the prognostic value and correlated pathways using various bioinformatic tools." (PMID 34442467, 2021). "Although it has been reported previously that higher expression of SOX4, SOX11, and SOX12 is negatively correlated with patient survival in various cancers, the expression of SOXC members has not yet been analyzed systematically in multiple cancer datasets." (PMID 34442467, 2021). "Aberrant elevation of SOX4, a member of SOX (SRY-related HMG-box) family transcription factors, has been identified in many types of human cancer and promotes cancer development." (PMID 33482915, 2021). "Some of the specific transcripts observed included those from the well-established cancer survival genes ALDH1A1, SURVIVIN, XIAP, HSPG2, BCL9, and SOX4." (PMID 34579762, 2021). "Among the genes in the SOX family, the expression of SOX4, SOX9, SOX11, and SOX12 was higher in multiple types of cancers than in their normal counterparts." (PMID 34442467, 2021). "The expression of genes related to SOX4, SOX11, and SOX12, which are highly upregulated in various types of cancers, and their related signaling pathways were also examined using a gene meta-analysis database." (PMID 34442467, 2021). "It has been demonstrated that SOX4 functions directly as a transcriptional activator of the EZH2 promoter and induces the expression of EZH2 in cancer cells." (PMID 34055896, 2021). "The overexpressing h-jou transfected cells were also enriched in potential cancer stem cell (CSC) markers, including SOX4, SOX8, CD44, MSI-2, EpCAM, and others." (PMID 33225905, 2020). "Second, this study only investigated the effects of circUBAP2/miR-361-3p/SOX4 pathway on CC cell proliferation, apoptosis and metastasis, whether or not the pathway involved in other cellular processes, such as cell cycle, and metabolism, to regulate cancer progression remains vague." (PMID 32760224, 2020). "TGFβ1 mediates the overexpression of SOX4, a member of the SOX (SRY-related HMG-box) family of transcription factors, which are known to be involved in developmental pathologies and cancer." (PMID 32586280, 2020). "Among the groups of SOX family proteins, group C includes three proteins present in most vertebrates: SOX4, SOX11, and SOX126,7; these proteins have been well studied in cancer and in important developmental processes." (PMID 30858360, 2019). "In other cancer cells, many genes have been identified as miR-338-3p targets, including ADAM17, PREX2a, ZEB2, Sox4, SMO, MACC1, and IRS2." (PMID 29618948, 2018). "Several members of SOX family stimulate the initiation and progression of different cancers, including SOX2 and SOX4." (PMID 29541384, 2018). "Downregulation of miR-204 in OSCC-derived cancer stem cells has been reported; up-regulation of miR-204 suppresses cancer stemness and epithelial-mesenchymal transition (EMT) properties by targeting SLUG and SOX4." (PMID 28423539, 2017).
cancer (continued). "Future research delineates the details of how miR-204 regulates its Slug/Sox4 axis, and how these interactions influence the EMT and cancer properties of OSCC remains to be determined." (PMID 26933999, 2016). "Three genes (SOX4, FOXM1, and FOXQ1) were subsequently chosen for further investigation based on their known role in colorectal or other human cancer types." (PMID 27119506, 2016). "Analysis of the SOX4 3′-UTR using microrna.org (maintained at cBio, the Computational Biology Center at Memorial Sloan-Kettering Cancer Center) predicted a miR-31 binding site." (PMID 25644061, 2015). "SOX4 – An Important Upstream Regulator of the EMT Program – SOX4 is a member of the Sox (SRY-related HMG-box) family of transcription factors and is frequently upregulated in various cancer types." (PMID 24840099, 2014). "Similar to SOX4, SOX2 and SOX9 have also been shown to have tumor suppressive effects in specific cancer types (gastric cancer and melanoma, respectively), further emphasizing the context specific nature of SOX involvement in carcinogenesis." (PMID 25594027, 2014). "In particular, SOX4, a known target of MIR129, facilitates differentiation of lymphocytes, and has been shown upregulated in various human cancers." (PMID 23406679, 2013). "Interestingly, SOX4, as a core component of TGF-β signal transduction, mediates EMT in various types of cancers." (PMID 40595502, 2025). "Moreover, it can regulate cancer cell proliferation and apoptosis by targeting different genes, including mitogen-activated protein kinase kinase kinase 3 (MAP3K3), SRY-box transcription factor 4 (SOX4), and methyltransferase like 3 (METTL3)." (PMID 39062744, 2024). "In addition, cancer stem cells (CSC) play an important role in cancer development and progression and SOX4 is one of the CSC regulators." (PMID 39118797, 2024). "The critical master regulators of CCC cancer cells were HNF1B and SOX4." (PMID 39149248, 2024). "Similarly, the decreased levels of SOX4, SOX9, Nanog,CD44, KLF4 and ABCG2 were observed from the harvested KYSE450 tumors related to miR-637 overexpression, indicating the inhibition of cancer cell stemness by miR-637." (PMID 36329557, 2022). "Thus, miR-873-5p served as a repressor in cancer development and DDP resistance in ESCC cells by targeting SOX4." (PMID 35241028, 2022). "We hypothesized that TEAD inhibition leads to VGLL3-mediated PIK3C2B and SOX4 induction, resulting in AKT activation, promotion of cell survival, and compromising the effects of TEAD–YAP blockade in cancer cells." (PMID 36347861, 2022). "SOX4, a member of the SOX (Sry-related high-mobility group (HMG) box) family of transcription factors, is reported to drive cancer development and progression through endowing cancer cells with survival, migratory, and invasive abilities." (PMID 33854048, 2021). "Furthermore, we also found that SOX4 directly binds to HDAC1 promoter and this SOX4-HDAC1 axis is conserved in multiple types of cancer cells." (PMID 33482915, 2021). "SOX4 is a member of the SOX (SRY-related HMG-box) family of transcription factors and increased SOX4 expression contributes to cellular transformation and EMT in many cancer types." (PMID 34055896, 2021). "SOX4 is a transcription factor as the member of the Sry‐related high‐mobility group box (SOX) family, and has been recognized to promote the development of various cancers." (PMID 34047469, 2021). "Furthermore, in this study, we confirmed the stimulatory effect of SOX4 on CRC cancer stemness, which demonstrated that targeting SOX4 holds the promise to eradicate not only normal differentiated cancer cells, but also undifferentiated CRC cells." (PMID 33482915, 2021). "We also found the expression of SOX4 were significantly upregulated regardless of the stage of cancer including COAD, LIHC, LUAD, and LUSC." (PMID 34442467, 2021).
cancer (continued). "SOX4 can activate multiple developmental pathways, including PI3K, Wnt, and TGFβ signaling, thus contributing to cell growth, EMT, and apoptosis inhibition in cancers." (PMID 32760224, 2020). "SOX4 is a member of the SOX (SRY-related HMG box) gene family which consists of transcription factors involved in the development and differentiation of cells and organs, as well as the initiation and development of cancers." (PMID 33005101, 2020). "Another Sox Group C member, SOX4, shares a similar function to SOX11 in human cancers." (PMID 30922366, 2019). "SOX4, a member of the SOX (sex-determining region Y-related HMG box) transcription factor family, has been reported to be abnormally expressed in a wide variety of cancers, and to exert a pleiotropic function." (PMID 26583330, 2015). "Although SOX4 expression has been discovered in various carcinomas, its role in CC is not well defined." (PMID 26583330, 2015). "For E2F3, SOX4, CBFB and SMARCC1, the transcript analyses were corroborated by an in-depth IHC analysis not only confirming their increased expression level, but also demonstrating their expression by the cancer cells." (PMID 19156145, 2009). "Furthermore, bioinformatic analysis of miR‐34a targets in various cancers identifies numerous target genes such as Jagged 1 (JAG1), CD44, SRY (sex determining region Y)‐box 4 (SOX4), Notch homolog 2 (NOTCH2), Matrix metallopeptidase 9 (MMP9), Interleukin 6 (IL‐6), and SMAD family member 4 (SMAD4)." (PMID 40336533, 2025). "Consistently, a recent study using a panel of cancer cell lines found that treatments with the TEAD inhibitor MGH-CP1 and YAP/TAZ silencing both promoted the VGLL3-mediated transcriptional activation of SOX4/PI3K/AKT signaling, which contributed to resistance to MGH-CP1." (PMID 38473214, 2024). "SOX4 belongs to the SRY-related HMG box family of TFs; it is related to embryonic development and cell-fate differentiation and promotes epithelial–mesenchymal transition and stemness of cancer cells, and TGF-β is related to the upregulation of its expression in cancer cells." (PMID 36661515, 2023). "Similarly, SOX4 binds to the promoter of HDAC1 in all types of tested cells, indicating the mechanism that SOX4 transcriptionally activates HDAC1 is conserved in multiple types of cancer." (PMID 33482915, 2021). "Six overexpressed oncogenes including BCL2, NOTCH1, SOX4, and CTNNB1 and 10 downregulated tumor suppressor genes including PRKCB, IRF1, CYLD, and TGFB1 were identified as the targets of the DE miRNAs, which may promote cancer development." (PMID 34336826, 2021). "Therefore, our analysis may contribute valuable insights into SOX4, SOX11, and SOX12 as a potential therapeutic goal for various human cancers." (PMID 34442467, 2021). "Since SOX4 regulates EMT of cancer cells by controlling EZH2 expression, we investigated whether miR-1251 could modulate the protein expression of EMT-related markers, SOX4 and EZH2 in PC cells." (PMID 34055896, 2021). "Circ-SOX4, identified as a novel circRNA, has not been studied in any cancer yet." (PMID 31911754, 2020). "This study is not the first to link SOX4 expression and clinical outcome of cancer." (PMID 19156145, 2009). "In Smad4-positive cancer cells, KLF5 is downregulated and Sox4, in the absence of KLF5, induces apoptosis by upregulating pro-apoptotic factors." (PMID 38569937, 2024). "IgAN endothelial cells also expressed increased levels of the transcription factor SOX4, a central component of TGF-β signaling to mediate EMT in various types of cancer, which has not been reported in IgAN yet." (PMID 33936064, 2021). "However, overexpression of miR-4516 did not influence TGF-β2-induced expression of SOX4, GRB2, and ETV4 in ARPE cells, although previous studies have reported that SOX4, GRB2, and ETV4 contribute to EMT in cancer cells." (PMID 35771766, 2022).